TRPV1 (transient receptor potential cation channel subfamily V member 1)
Diseases named in the same sentence as TRPV1 in open-access papers (continued):
Sharing a sentence is not in itself a finding about the gene and the disease.
Pruritus (48 papers, 2010 to 2026). Pruritus is an itch or a sensation that makes a person want to scratch. "Therapies targeting neurobiomarkers of ACD, including IL-31 and TRPV1 also show promise in reducing ACD- associated pruritus." (PMID 40181807, 2025). "A previous study suggested that the nerve growth factor–mediated TRPV1 pathway is associated with the regulation of neurogenic pruritus, defined as an unpleasant sensation of the skin that provokes the urge to scratch." (PMID 38474002, 2024). "Imiquimod, which has been previously used for generating psoriasis murine models, requires TRPV1-expressing neurons to cause pruritus." (PMID 36613861, 2022). "In the skin, TRPV1 plays an important role in neurogenic inflammation, pain and pruritus associated to many dermatological diseases." (PMID 33420359, 2021). "Next, we further clarified whether Gper deficiency affects the function of the TRPA1 and TRPV1 in TG neurons under the AEW‐induced chronic itch condition." (PMID 37452499, 2023). "In one study, IL-31-induced pruritus was significantly decreased in TRPV-1 deficient mice." (PMID 36613861, 2022). "TRPV1 is expressed in sensory nerve endings and keratinocytes in human skin, where it serves as a key mediator of burning pain, erythema, and pruritus." (PMID 41511362, 2026). "Despite their therapeutic potential in pain and pruritus management, TRPV1 antagonist development faces two main challenges: disruptions in systemic temperature regulation and their hydrophobic nature." (PMID 41596464, 2026). "Meanwhile, IL-31 initiates acute pruritus by engaging IL-31Rα on TRPV1+ sensory neurons, and TGF-β promotes IL-31 production in dermal conventional type 2 dendritic cells." (PMID 41596464, 2026). "The Asivatrep® cream (PAC14028), another selective TRPV1 antagonist, has shown effectiveness in alleviating pruritus in patients with atopic dermatitis." (PMID 41596464, 2026). "On the other hand, TRPV1 desensitization (usually produced by repeated treatment with the TRPV1 agonist capsaicin) can reduce the severity of psoriasis and pruritus." (PMID 41689746, 2026). "In vivo studies show that blocking TRPV1 disrupts IL-31 signaling, highlighting TRPV1 as a potential therapeutic target in pruritus." (PMID 41155460, 2025). "In the ovalbumin-induced atopic dermatitis model, intrathecal injection of IL-31 has been shown to evoke pruritus in mice, with the IL-31 receptor co-localizing in TRPV1-positive DRG neurons." (PMID 40095628, 2025). "The discovery of Hashimoto provided a new direction for researching the mechanism of Periostin-mediated pruritus in PS through the activation of TRPV1 and TRPA1." (PMID 37705977, 2023). "Transient receptor potential ion channel V1–expressing (TRPV1-expressing) C-fibers are essential for the generation of histamine-dependent and -independent pruritus." (PMID 36520531, 2023). "Pruritus induced by IL-31 is mediated by directly activating IL-31RA on the cutaneous TRPV1+ sensory nerve." (PMID 36874007, 2023). "Topical cooling has been used to reduce pruritus, for cooling decreases nerve excitability and conduction velocity and therefore slows some itch transduction pathways, such as the one involving TRPV1." (PMID 36613861, 2022). "Here, we revise this important topic and describe the pre-clinical validation of soft TRPV1 antagonists to treat peripheral chronic pain and pruritus." (PMID 36117910, 2022). "Taken together, cumulative evidence signals to TRPV1 as a central therapeutic target for alleviating chronic pruritus." (PMID 36117910, 2022). "Based on the important roles played by TRPV1 in skin inflammation and pruritus, the TRPV1 channel is another potential target for skin diseases." (PMID 35634308, 2022). "Thus, attenuation of TRPA1 and TRPV1 expression and their surface trafficking, plus inhibition of itch-related neuropeptide release from pruritic nerve would underlie the observed anti-pruritic activity of BoNTs in animal models of chronic itch and in patients with itch conditions." (PMID 34276687, 2021).
Pruritus (continued). "IL-31-induced pruritus was reported to be associated with TRPA1 and TRPV1 neurons; however, IL-31-mediated neuronal growth was independent of the TRPV1 channels." (PMID 34281281, 2021). "Although direct activation of TRPM3, similar to TRPV1, resulted exclusively in nociception and not itch, these results cannot exclude that TRPM3 signaling can also contribute to the sensory transduction of pruritus, as has been described for TRPV1." (PMID 33130130, 2021). "To further investigate the anti-pruritus mechanisms underlying HLJDT, we analyzed pruritus-related markers (i.e., JAK1, HRH4, IL-4αR, GRP, SP, and TRPV-1) from the dorsal root ganglion." (PMID 34925005, 2021). "Low-dose capsaicin topical patches have been widely used in treating pain and pruritus diseases through TRPV1 desensitization in clinical settings." (PMID 34691215, 2021). "Experiments revealed that IL-31 induces pruritus by binding to IL-31RA that is exclusively expressed on TRPV1+/TRPA1+ DRG neurons indicating TRP channels as key mediators of T-cell mediated IL-31-induced pruritus." (PMID 33681256, 2021). "In the present study, we surprisingly found thatablation of TRPV1-expressing C-fibers, which caused by systemic RTX treatment, didnot affect H2S donors-induced itch, but abolished compound 48/80 orchloroquine-induced itch in mice." (PMID 26602811, 2015). "The study was designed as a two part study in order to address the role of TRPV1 in pruritus and investigate the therapeutic potential of SB705498." (PMID 25047038, 2014). "In this study, we have investigated the roles of TLR4 in sensory transmission and found that TLR4 is required for optimal histamine-induced itch signal transduction through regulating TRPV1 activity." (PMID 25139109, 2014). "Activation of TRPV1 releases neuropeptides; the resulting neurogenic inflammation is believed to contribute to the development of pruritus." (PMID 25047038, 2014). "Our data therefore support a model in which TRPV1-expressing sensory neurons are important for histamine-induced itch." (PMID 20497578, 2010). "Since TRPV1 is involved not only in itch but also in pain perception, suppression of pruritus could relatively enhance pain sensitivity, potentially contributing to pain-related symptoms." (PMID 41464561, 2025). "Although TRPV1 is the primary ion channel involved in the transmission of itch signals in nociceptors, it is noteworthy that other ion channels in the DRG have also been implicated in pruritus induction by psoriasis." (PMID 38474002, 2024). "Several TRPV1 antagonists are in development for the treatment of pruritus, but with mixed results." (PMID 38139833, 2023). "The mechanism of skin neurogenic pruritus mediated by the TRPV1-mediated SP-NK1R signaling pathway may provide a new therapeutic target for PS pruritus conduction." (PMID 37705977, 2023). "Second, while our data strongly support the involvement of peptidergic neurons (IL-31RA+TRPV1+) in CTCL-associated pruritus, we do not exclude the role of nonpeptidergic neurons in which ATF3+ is expressed." (PMID 36520531, 2023). "TRPA1 and TRPV1 are also considered to play a key role in the AEW‐induced chronic itch behavior." (PMID 37452499, 2023). "Moreover, our results revealed that the mRNA expression levels of Trpa1, Trpv1, and Trpv4 were significantly increased in the DRGs of the dry skin-induced chronic itch model." (PMID 35095413, 2021). "In addition, TRPV1 is a downstream ion channel for the histamine H1 and H4 receptors to transmit itch signals." (PMID 34691215, 2021). "Here, we investigated the pharmacological properties of the lead antagonist, 2-((4-hydroxy-2-iodo-5-methoxybenzyl) amino)-2-oxoethyl dodecanoate (AG1529), on heterologously expressed human TRPV1 (hTRPV1), on nociceptor excitability and on an in vivo model of acute pruritus." (PMID 33420359, 2021).
Pruritus (continued). "Furthermore, 8% topical capsaicin patches also have a therapeutic effect in chronic pruritus, thus making targeting TRPV1 an attractive strategy for itch therapy." (PMID 34691215, 2021). "Given that scratching evoked by trypsin, which acts on PAR-1, PAR-2, and PAR-4, is suppressed by TRPV1 inhibition or TRPV1 knockout in mice, as well as by the H1-antihistamine cyproheptadine, trypsin-evoked pruritus is considered to be involved in histamine-dependent itch." (PMID 33668714, 2021). "Among these genes, the overexpression of the TRPV1 gene correlated with the severity of pruritus in psoriasis, and the interaction between TRPV1-immunoreactive fibers and dendritic cells has been shown to regulate the IL-23/IL-17 pathways and promote psoriatic inflammation." (PMID 33182442, 2020). "Because TDGA8 is more sensitive to acid than TRPV1, the acidosis-induced itch could fit in the spatial contrast theory, which states that itch arises from a sharp contrast between individual nociceptors firing among the surrounding silent neighbors." (PMID 30486810, 2018). "Studies suggest that TRPV1 may be involved in the development of pruritus in psoriasis." (PMID 36874007, 2023). "Interestingly, KRGE has also anti-pruritic effects on the histamine-dependent H1R/TRPV1 pathway, which might provide a dual anti-pruritic candidate agent for the treatment of pruritus patients." (PMID 33681256, 2021). "Thus algogenic function of TRPV1 on nociceptors can reciprocally attenuate MOR-induced itch." (PMID 30341332, 2018). "Within this integrated microenvironment, specific TRP channels, notably TRPA1, TRPV1, TRPV3, and TRPV4, exhibit a remarkable ability to simultaneously influence both fibrotic and pruritus-related signaling pathways." (PMID 41596464, 2026). "Mechanistically, activation of IL-31RA has been shown to sensitize TRPV1 and TRPA1 ion channels for pruritus." (PMID 36520531, 2023). "In this review, we discuss the role of TRP channels TRPA1, TRPV1, TRPV2, TRPV3, TRPV4, TRPM8, and TRPC3/4 in acute and chronic pruritus." (PMID 38139833, 2023). "However, the potent TRPV1 capsaicin is not ingestible and even topical capsaicin causes common side effects such as skin irritation, swelling, erythema and pruritus, suggesting that a mild TRPV1 agonist might be helpful for reducing side effects while reliving pain." (PMID 36080196, 2022). "In conclusion, these results indicate that both channels, TRPV1 and TRPA1, are involved in the transmission of histamine-induced pruritus." (PMID 34439832, 2021). "Several studies presented evidence showing that TRPV1 and TRPA1 play crucial roles in pruritus transmission." (PMID 33681256, 2021). "Accordingly, mice co-injected with TRPV1 and TRPV4 antagonists showed a decrease in chloroquine induced pruritus, indicating that TRPV1 and TRPV4 cooperate in transducing pruritogenic stimuli and in producing the scratch response." (PMID 32481620, 2020). "There have been reports that TRP channels other than TRPV3, such as TRPV1/4, TRPA1, and TRPM6/7 contribute to pruritus." (PMID 29140280, 2017). "It was shown that certain thermosensitive TRP channels, especially TRP vanilloid 1 (TRPV1), TRPV3, TRPV4 and TRP ankyrin 1 (TRPA1), have important roles in the pathogenesis of pruritus as well as pain." (PMID 29140280, 2017). "In this study, wesubsequently examined the role of TRPV1 and TRPA1 in H2Sdonors-induced itch using pharmacological methods." (PMID 26602811, 2015). "Numerous publications have identified the Transient Receptor Potential (TRP) channels (e.g. TRPV1, TRPV3, TRPA1, TRPM8) as having a key role in pruritus and Atopic Dermatitis (AD)." (PMID 25047038, 2014). "These receptors, which include GPCRs, cytokine receptors, and Toll-like receptors (TLRs), facilitate the opening of ion channels, particularly TRP channels like TRPV1 and TRPA1, and mediate receptor-operated calcium entry (ROCE), leading to the generation of pruritus action potentials." (PMID 41596464, 2026).
Pruritus (continued). "Thus, TRPV1+ afferents were critically required for the development and maintenance of CTCL-induced pruritus." (PMID 36520531, 2023). "In the present study, we mainly focused on the role of TMEM100 in the AEW itch model and the regulatory mechanism of TMEM100 in TRPV1 and TRPA1 functional changes to clarify the mechanism of the TRPV1 and TRPA1 functions modulated by TMEM100 during dry skin-induced itch." (PMID 36514220, 2022). "Although TRPV1 and TRPA1 are the major TRP ion channels that are directly involved in various types of pruritus, increasing evidence suggests that TRPV4 also plays an essential role in pruritus." (PMID 34925342, 2021). "Interestingly, chloroquine induces itch in a fashion that is dependent on TRPV4 expression in DRG neurons, where the TRPV1 channel is also expressed." (PMID 32481620, 2020). "In addition, a non-vanilloid TRPV1 antagonist, PAC-14028, has been shown to attenuate the inflammatory response and pruritus associated with dermatitis, as well as to prevent barrier damage and accelerate skin barrier recovery." (PMID 41226679, 2025). "Indeed, direct, general activation of TRPV1 is known to induce nociception and not itch, but TRPV1 expressed locally in pruriceptive sensory neurons takes part in the transduction of both histaminergic and some forms of non-histaminergic pruritus." (PMID 33130130, 2021). "In the AEW itch model, the itch-facilitating effect of TMEM100 is achieved mainly through the modulation of TRPA1 but not TRPV1." (PMID 36514220, 2022).
ischemia (43 papers, 2006 to 2025). A hypoperfusion of the BLOOD through an organ or tissue caused by a PATHOLOGIC CONSTRICTION or obstruction of its BLOOD VESSELS, or an absence of BLOOD CIRCULATION. "It has been postulated that TRPV1 senses a reduction of pH in tissues caused by infection, inflammation, or ischemia, which produces pain in mammals." (PMID 21779403, 2011). "In addition, TRPV1 is cardio-protective against ischemia, since TRPV1 null-mutant mice are more susceptible to myocardial infarction-induced, TGF-β1/Smad2-mediated myofibroblast activation and fibrinogenesis." (PMID 36277180, 2022). "In this study, we further showed that calcium influx occurs via the TRPV1 channel, which is demonstrated to play an important role to protect the heart against apoptosis during ischemia/reperfusion through upregulating the PI3K/Akt signaling pathway." (PMID 40427497, 2025). "In an ischemia model, TRPV1 activation through capsaicin treatment enhances aortic EC proliferation, ultimately contributing to collateral vessel growth." (PMID 39965247, 2025). "Administration of a TRPV1 antagonist via intracerebroventricular injection 30 min anterior to the onset of ischemia abated neurological and motor deficits and reduced infarct size." (PMID 37718934, 2024). "A TRPV1 antagonist, capsazepine (20 nmol), injected intracerebroventricularly 30 min before the onset of ischemia, attenuated neurological and motor deficits and decreased infarct size instead of influencing cerebral blood flow in the occluded MCA territory." (PMID 36527242, 2023). "The activation of TRPV1 participates in the correction and control of alterations in the levels of NO, cGMP, BH4 and CGRP caused by ischemia reperfusion damage." (PMID 35164296, 2022). "In other words, the activation of TRPV1 synchronized the NO pathway reactions that were altered by the ischemia and reperfusion events." (PMID 35164296, 2022). "TRPV1, which is activated after ischemia intensely mediate astrocyte activation compared to microglia, increases IL-1β release and exacerbates ischemia-induced brain damage (brain atrophy, infarct size, and neurobehavioral loss)." (PMID 31142341, 2019). "On the other hand, similar to our study, TrpV1 activation as a therapeutic target has been tested in a mouse model of ischemia." (PMID 30417826, 2018). "In conclusion, TRPV1 channels modulate the severity of ischemia-reperfusion injury through direct and indirect effects that elicit divergent responses." (PMID 25314299, 2014). "TRPV1 is reported to be activated by mediators and secondary messengers in inflammatory conditions and with tissue injury and ischemia." (PMID 23258994, 2012). "Emerging studies have shown that capsiate, a metabolite of the gut microbiota, upregulates GPX4 expression by activating transient receptor potential cation channel subfamily V member 1 (TRPV1), thereby inhibiting ferroptosis and protecting the intestine from ischemia/reperfusion injury." (PMID 40335466, 2025). "First, calcitonin gene-related peptide was investigated, as this neuropeptide is released by sensory neurons upon the activation of TRPA1 and TRPV1, which are sensors of noxious compounds including reactive oxygen species and acidosis, that occurs during ischemia." (PMID 39200320, 2024). "The effect of TRPV1 in ischemia has been confirmed in the permanent MCAO model." (PMID 36527242, 2023). "The strategy to use OLDA to activate TRPV1 intrathecally and chronically may be applied to other fields such as the protection of afferent nerves against ischemia/reperfusion-induced nerve injury." (PMID 37047183, 2023). "As TRPV1-knockout mice have exacerbated post-ischemia inflammation and injury, it is important to highlight that TRPV1K710N mice could have reduced post-insult pain behaviors without increased cellular injury." (PMID 36472910, 2023). "Therefore, in this paper we tested the role of TRPV1 in the possible restoration of cardiac function in ischemia and reperfusion." (PMID 35164296, 2022).